EGFR (epidermal growth factor receptor)
Diseases named in the same sentence as EGFR in open-access papers (continued):
Sharing a sentence is not in itself a finding about the gene and the disease.
lymph node metastasis (continued). "EGFR is significantly associated with stage, lymph node metastasis, lymphatic vessel invasion, and perineural invasion in ECC." (PMID 32708604, 2020). "Expression of EGFR > 35% was associated with the presence of lymph node metastases (p = 0.001), liver metastases at diagnosis (p < 0.001), advanced stages of the disease (p < 0.001) and KRAS mutations (p = 0.001)." (PMID 32170146, 2020). "In ADC patients, PD-L1 positivity was associated with a wild-type EGFR status (p=0.046) and with the presence of lymph node metastasis (p=0.022)." (PMID 32765198, 2020). "We found that high 14-3-3ζ expression was significantly associated with advanced T stage, advanced TNM stage, the presence of lymph node metastasis, and poor treatment response to EGFR-TKI in LUAD patients with EGFR-activating mutations." (PMID 33123465, 2020). "The recent Korean study found that ctDNA detection was associated with poorer PFS in patients treated with EGFR TKIs, and also identified ctDNA detection and extrathoracic lymph node metastasis as independent factors predicting poorer PFS." (PMID 31652678, 2019). "The present study confirmed several previously reported risk factors for BM: the female gender, age under 60 years, adenocarcinoma, N2 or N3 lymph node metastases, and mutation at EGFR 19 exon." (PMID 31498117, 2019). "Wang el al. reviewed nine studies comparing EGFR mutation status between primary and matched lymph node metastases in NSCLC and found that the overall discordance rate of 12.2%." (PMID 31216329, 2019). "A total of 60 cases with pleural invasion were found, including 43 and 17 patients with mutated and wild-type EGFR, respectively; there were 32 cases of lymph node metastasis, including 22 and 10 patients with mutated and wild-type EGFR, respectively." (PMID 28253871, 2017). "In patients with EGFR mutation, pleural invasion, endobronchial metastasis, and lymph node metastasis rates were 62.5, 39.1, and 34.4%, respectively, indicating statistically significant differences (p = 0.003)." (PMID 28253871, 2017). "Among the 64 patients with EGFR mutation, pleural invasion, endobronchial metastasis, and lymph node metastasis rates were 62.5% (43/64), 39.1% (25/64), and 34.4% (22/64), respectively, showing statistically significant differences (p = 0.003)." (PMID 28253871, 2017). "The proportion of mPAP element was consistently and significantly greater in EGFR-mutated LADCs with lymph node metastasis than in any of the other groups." (PMID 27861549, 2016). "Associated with prognosis (lymph node metastasis, clinical stage and EGFR mutation and patients survival)." (PMID 27081087, 2016). "The proportions in the EGFR-mutated LADCs with lymph node metastasis were compared with those in the other three groups." (PMID 27861549, 2016). "In surgically resected tumors, the EGFR-mutated LADCs with lymph node metastasis had the micropapillary element in a significantly greater proportion than others (Mann-Whitney tests P ≤0.026)." (PMID 27861549, 2016). "We also found that the rates of lymph node metastasis and EGFR gene amplification were significantly associated with patient OS both in univariate and multivariate analyses." (PMID 26115045, 2015). "CXCR4 expression was significantly associated with lymph node metastasis (P = 0.001), and EGFR/CXCR4 coexpression was significantly associated with lymph node metastasis (P = 0.026), TNM stage (P = 0.048), and poor tumor differentiation (P = 0.004)." (PMID 25679210, 2015). "EGFR amplification was associated with the lymph node metastasis (P = 0.028), while high polysomy wasn’t associated with this factor (P = 0.227)." (PMID 25953424, 2015). "EGFR overexpression was also found in CC and was associated with lymph node metastasis, tumor stage, lymphatic vessel and perineural invasion and revealed EGFR as an independent significant prognostic marker and a risk factor for tumor recurrence in CC." (PMID 26729094, 2015).
lymph node metastasis (continued). "In a study with 236 cases of CC, EGFR overexpression was associated with lymph node metastasis, tumor stage, lymphatic vessel invasion and perineural invasion in extrahepatic CC." (PMID 26729094, 2015). "High EGFR expression was associated with tumor invasion, lymph node metastasis, numbers of lymph node metastases, and UICC 2002 and 2010 TNM stages in these esophageal cancer patients." (PMID 24131756, 2013). "Significant associations were noted between SUVmax and tumor size, lymph node metastasis, histologic grade, ER and PR expression, EGFR and Ki-67." (PMID 22741544, 2012). "In our study among five patients with EGFR TKI-sensitive mutations in mediastinal lymph node metastases, there were four patients who showed tumor regression in response to EGFR TKI and underwent surgery." (PMID 21414214, 2011). "Adenocarcinoma, clinically undetected lymph node metastasis (cN0 or unknown), EGFR mutation, and the combination of postoperative chemotherapy or TKI were identified as better prognostic factors in OS in univariate analysis." (PMID 37355521, 2023). "In conclusion, our meta-analysis provides an evidence-based report that EGFR overexpression is a very frequent oncogenic mechanism in oral oncogenesis that is associated with a worse survival rate and a higher risk of developing lymph node metastases." (PMID 37569265, 2023). "Additionally, it has been shown that tissue expressions of certain biomarkers, such as Cytokeratin, Podoplanin, Vimentin, Programmed Cell Death Ligand-1, or Epidermal Growth Factor Receptor, are significantly associated with the risk of lymph node metastasis." (PMID 37373623, 2023). "In addition, positive EGFR mutation appears to be associated with low risk of lymph node metastasis." (PMID 36401689, 2022). "Among the EGFR mutation positive samples, 12 (42.9%) showed lymph node metastasis, followed by the brain (n = 6; 21.4%), multiple sites (n = 5,17.95%), two (7.1%) each showed pleural fluid and bone metastases, and one (3.6%) sample showed metastasis to the femur." (PMID 36613084, 2022). "In addition, our result was different from previous data that suggested that EGFR amplification was associated with lymph node metastases." (PMID 35723316, 2022). "Moreover, LUAD patients harboring the WT EGFR and a T allele rs8193036 polymorphism had higher risks of developing advanced-stage tumors and lymph node metastasis." (PMID 33802737, 2021). "In addition, the same study showed that PD-L1 expression was also associated with male gender, smoke, lymph node metastasis, EGFR wild-type status, KRAS mutations, and overall survival." (PMID 33155793, 2021). "Moreover, in our study, EGFR mutations were associated with a small tumour size and lymph node metastasis proven by surgery, suggesting a low TNM stage in those cases." (PMID 33707479, 2021). "In addition, high 14-3-3ζ expression was associated with advanced T stage, TNM stage, presence of lymph node metastasis and, importantly, poor treatment response to EGFR-TKIs in LUAD patients with EGFR-activating mutations." (PMID 33123465, 2020). "Moreover, the male population harboring a mutant EGFR and T allele rs9862 polymorphism had a higher risk of developing advanced stage tumors and lymph node metastasis." (PMID 33126605, 2020). "In addition, the expression levels of LAPTM4B were positively correlated with advanced clinical stages, lymph node metastasis and EGFR mutations." (PMID 30940109, 2019). "In addition, some studies suggested that VEGFA expression has a significant association with EGFR mutations, advanced clinical stage and lymph node metastasis." (PMID 30972298, 2019). "Then, we investigate LAPTM4B protein levels in 63 LAC tissues by IHC and our results revealed that high expression of LAPTM4B correlated with aggressive clinicopathological features (including advanced clinical stages, lymph node metastasis and EGFR mutations)." (PMID 30940109, 2019).
lymph node metastasis (continued). "EGFR overexpression was further associated with lymph node metastasis as well." (PMID 29455652, 2018). "We hypothesized that the number of EGFR gene copy alterations in the primary tumor can predict whether tumors will reoccur or whether patients will be at risk for lymph node metastasis." (PMID 28854970, 2017). "However we did note that in patients with wild type EGFR and lymph node metastases, P-s207 LysRS nuclear expression appear to be associated with worse prognosis." (PMID 29029422, 2017). "The associations of EGFR mutation with pleural invasion, endobronchial metastasis, and lymph node metastasis were analyzed according to pathologies of pleural invasion and lymph node metastasis, as well as EGFR gene mutation detected by postoperative pathological specimens." (PMID 28253871, 2017). "However, lymph node metastasis rates were similar between EGFR mutated and wild-type patients (34.4 vs 25.6%, respectively, p > 0.05)." (PMID 28253871, 2017). "In addition, endobronchial metastasis incidence was higher than that of lymph node metastasis, suggesting the influence of EGFR mutation on resection scope." (PMID 28253871, 2017). "Besides, EGFR expression was noted to possess prognostic value for that its expression was significantly associated with lymph node metastasis in a retrospective analysis of 168 patients with PTC." (PMID 27703281, 2016). "Moreover, the pooled odds ratios (ORs) revealed associations between EGFR expression and clinicopathological features, such as lymph node metastasis (OR: 1.72, 95% CI: 1.23–2.40) and tumor size ≥4 cm (OR: 1.64, 95% CI: 1.20–2.23)." (PMID 27438047, 2016). "In our study, EGFR expression was closely associated with extensive lymph node metastasis with high ND, suggesting that the EGFR might be a causative molecule for such aggressive phenotypes." (PMID 25154973, 2015). "Expression of EGFR in NSCLC is associated with frequent lymph node metastasis and chemo-resistance." (PMID 25474037, 2014). "However, amplification of both ERBB2 and EGFR were significantly associated with the depth of invasion of the tumor and with lymph node metastasis." (PMID 21689422, 2011). "For example, in some statistical analyses of selected subgroups (e.g., lymph node metastasis status in LUAD patients with WT EGFR), the rather small number of patients might cause that the statistical significance p value was practically irrelevant (p = 0.049)." (PMID 33802737, 2021). "Among these patients, EGFR T790 M mutation was detected in 23 patients via body fluids (19 pleural effusion, 2 ascites, and 2 cerebrospinal fluid), and in 69 patients in other specimen types, such as primary lesions, lymph node metastases, other tissue samples and plasma samples." (PMID 31183631, 2020). "Lymph node metastasis (P=0.024) and overexpression of EGFR (P=0.041) were the only independent variables associated with poor survival, with a risk ratio of 4.22 for lymph node metastasis (95% CI=1.21–14.74), and 5.88 for EGFR overexpression (95% CI=1.07–32.31)." (PMID 12915878, 2003). "Its involvement has been linked to the recurrence, lymph node metastasis, and chemoresistance of EOC by modulating EGFR activity, resulting in poor prognosis." (PMID 39030559, 2024). "In patients with pADCs carrying EGFR mutations, CAGE and ATG5 were more frequently expressed in those manifesting lymph node metastasis." (PMID 37735252, 2023). "The dysregulation of STC2 was reported as a major risk factor of EGFR tyrosine kinase inhibitor (TKI) resistance in non-small cell lung cancer (NSCLC) and a predictive marker for lymph node metastasis in esophageal squamous cell carcinoma." (PMID 36589233, 2022).
lymph node metastasis (continued). "The correlation rates between primary lesion and lymph node metastases were only 67.1% (53/79) for EGFR, 63.3% (50/79) for HER2, and 74.7% (59/79) for HER3." (PMID 35902718, 2022). "For EGFR, Wei22 reported a 69.6% correlation rate of EGFR scores between primary tumors and lymph node metastases, which is close to our findings (67.1%)." (PMID 35902718, 2022). "In the 79 patients, majority (52, 65.8%) of the primary lesions showed high EGFR expression (2+/3+), compared to 46 (58.2%) in lymph node metastases." (PMID 35902718, 2022). "Multivariate Cox regression analysis showed that Beclin 1, EGFR, ALK mutations, tumor differentiation grade, TNM stage and lymph node metastasis were independently associated with PFS." (PMID 36401689, 2022). "In our study, high EGFR expression (2+ and 3+) was more commonly seen: 65.8% in primary tumor and 58.2% in lymph node metastases." (PMID 35902718, 2022). "Regarding EGFR expression, study by Wei22 reported high EGFR expression (2+ and 3+) in 29% of primary lesions and 14% of lymph node metastases." (PMID 35902718, 2022). "The G12C group had a higher frequency of distant lymph node metastasis (10% vs. 2%, p = 0.02) than did the EGFR+ group." (PMID 34298783, 2021). "Next, we evaluated the correlation between the IRGPs signature and clinical characteristics (age, gender, smoking, EGFR mutation, KARS mutation, radiotherapy, chemotherapy, TNM stage, tumor size, lymph node metastasis, and distant metastasis)." (PMID 33574499, 2021). "Previous studies employing IHC analysis have shown an association between EGFR expression and liver metastasis in sCRC patients; here, we also found that EGFR-positive tumors had lymph node metastases and a higher TNM category at diagnosis." (PMID 32170146, 2020). "POI, level of differentiation, and expression of EGFR are independent prognostic markers for lymph node metastasis." (PMID 33123565, 2020). "Within male patients harboring a mutant EGFR, TIMP-3 rs9862 T (CT+TT) allele carriers were at higher risk of developing an advanced stage (p = 0.025) and lymph node metastasis (p = 0.043)." (PMID 33126605, 2020). "On multivariate analysis, higher SUVmax and the presence of lymph node metastasis and wild-type EGFR were independent predictors of PD-L1 positivity." (PMID 32765198, 2020). "Statistically significant relationship between lymph node metastasis and survival rates with higher expression of EGFR was identified in the present study (p < 0.05)." (PMID 33123565, 2020). "Serum LAPTM4B levels of LAC patients were significantly correlated with smoking, advanced clinical stages, lymph node metastasis, anaplastic lymphoma kinase (ALK) rearrangements and EGFR mutations." (PMID 30940109, 2019). "EGFR and CCDN1 amplification have been associated with clinical stage, tumour differentiation, and lymph node metastasis in HNSCC." (PMID 31703248, 2019). "In the AC subgroup multivariate analysis demonstrated that male status, tumor size, lymph node metastases and the expression of EGFR were independent prognostic indicators for OS." (PMID 31319607, 2019). "An inverse association has been shown between EGFR expression and survival rate of ESCC patients in which higher levels of EGFR are associated with chemo-radiotherapeutic resistance and lymph node metastasis." (PMID 30202417, 2018). "An overexpression of EGFR was observed in 49% of the cases and it was correlated with clinical stage and lymph node metastasis significantly." (PMID 29455652, 2018). "All ACs were derived from patients who did not receive any preoperative or postoperative treatment and were classified according to the tumor grade, lymph node metastasis, and the KRAS and EGFR mutational status." (PMID 28860622, 2017). "The concordance rate of EGFR gene copy number in primary tumors and lymph node metastasis was 68.4% (McNemar test: p = 0.389)." (PMID 28854970, 2017).
lymph node metastasis (continued). "In conclusion, the present meta analysis demonstrated that high EGFR expression is correlated with poor OS, tumor differentiation, lymph node metastasis and tumor stage." (PMID 28199988, 2017). "High levels of EGFR and Tid1-S were detected in the mitochondria of cancerous lesions from stage IV NSCLC patients, and high levels of mitochondrial Tid1-S/EGFR were correlated with lymph node metastasis and poor overall survival of NSCLC patients." (PMID 28714950, 2017). "Lymph node metastasis had strong prognostic implications in both the EGFR-negative and EGFR-positive subgroups (HR > 1.0, p < 0.050 for both univariate analysis and multivariate analysis)." (PMID 27399694, 2016). "The circulating EphB4 mRNA was closely correlated with the histopathological type (p = 0.032) while the circulating EGFR mRNA was closely correlated with the lymph node metastasis (p = 0.023)." (PMID 27827952, 2016). "For the patients with lymph node metastasis, 52.8% (85/161) cases showed EGFR protein overexpression and 26.1% (42/161) demonstrated EGFR FISH positivity." (PMID 27013591, 2016). "EGFR overexpression was significantly correlated with clinical stage and lymph node metastasis (p<0.05)." (PMID 27013591, 2016). "Secondly, the correlation of EGFR expression with clinical features and prognosis were evaluated by scoring system 1 to 6, 1 and 4 related to lymph node metastasis, however, only 1 showed a statistically significant prognosis with DFS (0.006) and OS (0.007)." (PMID 25953424, 2015). "The multivariate Cox proportional hazards model analysis showed that ADAM17, EGFR, lymph node metastasis and TNM stage all had independent prognostic significance (all P<0.05)." (PMID 25351873, 2015). "EGFR overexpression according to scoring system 1 and 4 was significantly correlated with the vascular invasion, lymph node metastasis (P < 0.05)." (PMID 25953424, 2015). "EGFR overexpression was revealed to correlate with the presence of lymph node metastasis and poor survival." (PMID 24944678, 2014). "The expression of EGFR was highest in the lymph node metastasis group (89.55%) and exhibited a positive correlation with lymph node metastasis (χ2=5.0690, P=0.0240)." (PMID 24649232, 2013). "The reduced expression of RBM5 protein was associated with tobacco smoke, tumor stages, and lymph node metastasis of NSCLC, while overexpression of EGFR and KRAS proteins was associated with tumor stages and lymph node metastasis of NSCLC." (PMID 22537942, 2012). "Overexpression of EGFR and KRAS proteins was associated with lymph node metastasis and with a more advanced pathologic stage." (PMID 22537942, 2012). "Of patients with lymph node metastases, EGFR gene amplification was present in 34.1% (14/41) of the cases." (PMID 21689422, 2011). "Although the current report is limited by the small sample size, our observations suggest that positive EGFR expression is relatively well-preserved during the metastatic progression from primary NSCLC to lymph node metastases." (PMID 20096104, 2010). "According to the results, EGFR expression is correlated with lymph node metastasis and histological grade." (PMID 20181250, 2010). "EGFR expression (1+/2+/3+) was found in 76.6% of the primary lesions and 78.7% of the lymph node metastases." (PMID 20096104, 2010). "The heterogeneity of EGFR gene status in neoplastic tissues obtained at different sites from the same patient is confirmed by our findings in lymph node metastasis." (PMID 19293803, 2009). "In contrast, elevated p-EGFR expression has been reported to correlate with lymph node metastasis in patients with adenoid cystic salivary gland tumors, supporting the hypothesis that elevated p-EGFR expression facilitates lymphatic metastasis." (PMID 40738059, 2025).